FGF2 (fibroblast growth factor 2)
Diseases named in the same sentence as FGF2 in open-access papers (continued):
Sharing a sentence is not in itself a finding about the gene and the disease.
prostate carcinoma (continued). "Additionally, androgen stimulates the activity and production of FGF2 and FGF-binding protein in PC3 prostate cancer cells with stably overexpressed AR." (PMID 28077787, 2017). "Although FRS2 expression is not regulated by androgen, androgen-sensitive prostate cancer cells express FGF2, and its expression is upregulated in response to androgen stimulation." (PMID 28077787, 2017). "FGF2 regulates angiogenesis and by binding to its receptor FGF2R, which is expressed in vinous cancer cells, including non-small cell lung cancer (NSCLC), gastric carcinoma and prostatic cancer." (PMID 26575424, 2015). "Furthermore, ARPCA inhibits the FGF8b/FGF2-driven growth and vascularization of TRAMP-C2 tumors, an androgen-responsive murine model of prostate carcinoma." (PMID 25912421, 2015). "In Lapointe prostate cancer dataset, FGF2 expression had no statistically significant between metastatic cancer and primary PCa tissues (-0.91190 ± 0.62090 vs. 0.57764 ± 0.35019, P = 0 .174)." (PMID 26650737, 2015). "However, in view of the limited co-culture time and capacity, we can not exclude the possibility that HUVEC will precondition prostate cancer cells to produce FGF2 in the co-culture system with prolonged co-culture." (PMID 33425737, 2020). "In addition, to examine whether FGF2 expression was regulated by docetaxel, we carried out additional assays of FGF2 expression in HUVEC co-cultured with prostate cancer cells following docetaxel treatment." (PMID 33425737, 2020). "Interestingly, the expression of FGF2 in HUVEC co-cultured with prostate cancer cells following docetaxel treatment (10nM for 48h) did not change compared with that in HUVEC co-cultured with prostate cancer cells without docetaxel treatment measured by qPCR." (PMID 33425737, 2020). "Moreover, blocking FGF2 by using PD173074 could reverse the enhancing effects of HUVEC on ERG expression and docetaxel resistance in prostate cancer cells." (PMID 33425737, 2020). "We have shown previously that reactive stroma promotes prostate cancer progression via induction of angiogenesis and the downstream actions of TGF-β1 induced factors in reactive stroma including connective tissue growth factor (CTGF) and fibroblast growth factor 2 (FGF-2)." (PMID 21060787, 2010). "However, we can not obviate the possibility that FGF2 secreted by prostate cancer cells may occur in more advanced prostate cancer because most of the immunohistochemical studies of FGF2 focused on radical prostatectomy specimens." (PMID 33425737, 2020). "However, when FGF2 antagonists were used to block the interactions between endothelial cells and prostate cancer cells, the expression of ERG could not be completely reversed." (PMID 33425737, 2020). "However, for mice prostate cancer organoids, FGF10, FGF2, PGE2, Nicotinamide and SB202190 were not necessary." (PMID 37576596, 2023). "In addition, we demonstrated that FGF-R expression in prostate cancer cells did not augment whether co-cultured with HUVEC or following docetaxel treatment, which suggested that the increasing FGF2 derived from HUVEC cells was the primary factor that contributed to the FGF2/FGFR signaling pathway." (PMID 33425737, 2020).
lung carcinoma (82 papers, 2006 to 2025). "FGF2 expression has been observed to be elevated in lung cancer and is associated with a bad prognosis." (PMID 37760616, 2023). "Fibroblast growth factor 2 (FGF2), secreted by cancer-associated fibroblast (CAFs), was reported to be required for tumor cell growth in lung cancer." (PMID 36189305, 2022). "FOXF1 has also been shown to contribute to the tumour-promoting properties of lung cancer-associated fibroblasts, including the production of hepatocyte growth factor and fibroblast growth factor-2, both of which promote tumour growth." (PMID 30624614, 2019). "Similarly, as is the case for rs308395 in the FGF2 gene, rs444903 is associated with the course of many cancers, including lung cancer." (PMID 27835972, 2016). "In lung cancer cells, depletion of eIF4H enhances sensitization to chemotherapy, decreases cell migration and inhibits tumor growth in vivo, in association with reduced translation of mRNA encoding cell-proliferation (c-Myc, cyclin D1) angiogenic (FGF-2) and anti-apoptotic factors (CIAP-1, BCL-xL)." (PMID 26498689, 2015). "Other highly significant features include sHER2/sEGFR2/sErbB2, AXL, TGFa, and FGF2, demonstrating strong predictive power in lung cancer classification." (PMID 40217526, 2025). "In vitro assay showed that HNRNPF and FGF2 promoted lung cancer cell proliferation and migration and were also involved in cell death." (PMID 37968457, 2023). "The results of the CCK-8 assay and EDU assay proved that the knockdown of HNRNPF and FGF2 obviously inhibited lung cancer cells proliferation." (PMID 37968457, 2023). "FGF2-mediated activation of FGFR1 promotes resistance to EGFR inhibitors in lung cancer, FLT3 inhibitors in AML, and KIT inhibitors in gastrointestinal stromal tumors." (PMID 37598282, 2023). "FGFs, especially FGF1 and FGF2, play a complex and context-dependent involvement role in lung cancer." (PMID 37760616, 2023). "In lung adenocarcinoma, linc00265 was uncovered to interact with miR-7 and subsequently upregulate fibroblast growth factor 2 (FGF2), contributing to lung cancer tumorigenesis." (PMID 35692754, 2022). "FoxF1, a downstream effector of HH signaling, stimulates the secretions of HGF and FGF2 by lung cancer fibroblasts, promoting lung cancer cell growth and migration in vivo." (PMID 35433472, 2022). "This ligand trap has been shown to be able to block FGF2-dependent cell proliferation and inhibit the growth of several cancers in xenograft models, including FGFR1-amplified lung cancer and FGF2-overexpressing mesothelioma." (PMID 34830951, 2021). "Previous studies confirmed that FGF2 exerts its biological function via combining FGF receptor 1(FGFR1) in lung cancer cells." (PMID 34873170, 2021). "The present findings support the need for a combinatorial strategy to treat lung cancer or other types of cancers that are heavily depending on FGF2." (PMID 34203430, 2021). "FGF2 (fibroblast growth factor 2) was reported to be overexpressed in many types of human cancer, for example, gastric cancer, lung cancer, and BC." (PMID 32775417, 2020). "Disruption of FGF2 expression results in elevated serum FGF2 levels, which is an independent poor prognostic factor for lymphoma, lung cancer, and sarcoma patients." (PMID 23988031, 2013). "In lung cancer cells, it has been demonstrated that targeting FGF2 could inhibit the cell growth mediated by the FGF2‐FEFR pathway." (PMID 40845073, 2025). "FGF2 is upregulated in lung cancer and is correlated with reduced patient survival." (PMID 40056285, 2025). "Inhibitors and drugs targeting FGF2 can effectively inhibit the development of lung cancer." (PMID 39497721, 2024). "Repressing expression of FGF2 can inhibit cancer cell proliferation and metastasis in lung cancer." (PMID 37057280, 2023). "Moreover, the correlation of FGF2 with tumor cell migration/ invasion has been explored in multiple tumors, such as cervical cancer and lung cancer." (PMID 37980162, 2023).
lung carcinoma (continued). "Among these genes, the genes that contributed the most to necroptosis and ICD-related risk models including necroptosis-related gene “HNRNPF” and ICD-related gene “FGF2”, respectively, were selected and performed in vitro experiments to verify the function of lung cancer." (PMID 37968457, 2023). "Furthermore, when we screened 135 lung cancer and 1,182 other cancer cell lines, numerous cells that expressed high FGF2 or FGF9 showed relatively higher expression levels of FGFR1, FGFR2, or both." (PMID 37880373, 2023). "The knockdown of HNRNPF and FGF2 inhibited the proliferation and migration of lung cancer cells." (PMID 37968457, 2023). "A study on pemetrexed-resistant lung cancer cell lines showed that high concentration of miR-124-3p, which was upregulated in BMs in our study, can decrease pemetrexed resistance by inhibiting the FGF2–EGFR pathway." (PMID 36613642, 2022). "In addition, FGF2 secreted by CAFs was found to contribute to lung cancer cells growth through overexpression of Tgfb, Mmp7, Fgf2, Fgf9, enhanced collagen synthesis, and increased expression of inflammatory cytokines such as Csf1, Cxcl12, and Ccl2." (PMID 34830951, 2021). "Furthermore, treatment of A549 and NCI-H292 cells with AG490, a JAK2 inhibitor, reduced FGF2 expression, proving that the JAK2/STAT3 pathway is associated with FGF2 modulation in lung cancer cells." (PMID 33121202, 2020). "Moreover, it has been confirmed that FGF2 participates in many malignant diseases, including myeloproliferative syndromes, lymphomas, lung cancer and so on." (PMID 32210363, 2020). "Although these results indicated that both FGF2 and TS might be involved in the development of pemetrexed resistance in lung cancer cells, TS might contribute to the emergence of resistance to a greater extent than FGF2." (PMID 30838090, 2019). "FGF2 has been reported to be involved in the resistance to anticancer agents, both cytotoxic chemotherapeutic and molecular-targeted, in various malignant tumors including lung cancer." (PMID 30838090, 2019). "Thus, the effects induced by FGF2 were different in each lung cancer cell line, although the expression of FGF2 was similarly upregulated during the development of pemetrexed-resistance." (PMID 30838090, 2019). "To determine whether human FGFR1 will be activated in this mouse system we demonstrated, that murine FGFR1 ligands, such as FGF1 and FGF2 can activate human FGFR1 using the human H520 lung cancer cell line that overexpresses FGFR1." (PMID 27391347, 2016). "In this study, expression data taken from a broad panel of mesothelioma cells and lung cancer cell lines demonstrated that high levels of FGF2 and/or FGFR1 RNA expression correlated with the antiproliferative effects of two FGF pathway inhibitors that differ in their mechanism of action." (PMID 27223434, 2016). "Moreover, msFGFR2c significantly inhibited the proliferation of FGFR1IIIc-positive NCI-H1299 lung cancer cells by the suppression of FGF-2-induced FGFR1 activation and suppressed the growth of NCI-H1299 transplanted tumors in nude mice." (PMID 28049184, 2016). "Additionally, lung cancer cells that depend on the FGF2/FGFR pathway may be prevented from proliferating using the FGF2 aptamer, which inhibits FGF2 activity." (PMID 37108717, 2023). "Based on the encouraging data with a lung cancer cell line presented here, future work may explore the influence or activity of ligand receptors outside and inside cancer cells and the intracellular trafficking of ABNs and the release of FGF-2." (PMID 32230722, 2020). "Thus, the increased expression of FGF2 appears to confer resistance to various cytotoxic chemotherapeutic agents in cancer cells, which is consistent with our results obtained for pemetrexed-resistant lung cancer cells." (PMID 30838090, 2019).
lung carcinoma (continued). "We reported that in afatinib-resistant sublines derived from the lung cancer cell line PC9 that harbors an activating EGFR mutation, the levels of multiple EGFR family proteins are markedly reduced and accompanied by compensatory activation of an FGF2/FGFR1 autocrine signaling pathway." (PMID 29050315, 2017). "Our in vitro experiments demonstrated that COX6A1 knockdown in lung cancer cells led to the upregulation of TGFB2, CXCL12, and FGF2." (PMID 40331946, 2025). "Internalized fibroblast growth factor (FGF-2)-loaded NPs increased nuclear ERK1/2 content and resulted in lung cancer cell death." (PMID 37538179, 2023). "A set of genes involved in epithelial cell growth (ERBB2, EGF, and FGF2) and Plasminogen (PLG) were connected to Cancer and Lung cancer in the Year 2 SPP1 network." (PMID 37513116, 2023). "We next determined the expression levels of HNRNPF and FGF2 in HBE and different lung cancer cell lines." (PMID 37968457, 2023). "Our studies highlight the broad therapeutic potential of RBM-007 and the multifunctionality of FGF2 in the treatments of wet AMD, achondroplasia, cancer pain and lung cancer, respectively, while providing perspectives on these therapeutic applicabilities." (PMID 34203430, 2021). "In lung cancer cell lines (H1581 and DMS114), FGF2-dependent activation of the FGFR1/ERKs pathway led to upregulation of SOX2 (Sry-related HMG box 2), which in turn promoted EMT and cell migration." (PMID 34830951, 2021). "Lung cancer CD133+ cells grew indefinitely as tumor-spheres in serum-free medium supplemented with epidermal growth factor and basic fibroblast growth factor (FGF-2)." (PMID 32260363, 2020). "FGF2, FGF9 and FGF10 can stimulate proliferation, treatment sensitivity, and apoptosis of lung cancer cells." (PMID 27166269, 2016). "This was also observed in FGF2- and FGF9-high expressing patients with bronchus and lung cancer." (PMID 37880373, 2023). "However, three hub genes JUN, FGF2, CCND1 and IL6 expressed fewer mRNAs in lung cancer tissues than normal lung tissues." (PMID 32210363, 2020). "MiR-210 in lung cancer cell-derived EVs is transferred to fibroblasts, where it inhibits TET expression, leading to CAF differentiation, activation of JAK/STAT signaling, and expression of pro-angiogenic VEGF, MMP9, and FGF2." (PMID 32957712, 2020). "Nevertheless, we suggested that BIRC5, FGF2, RTKN2 and SLIT3 may be important for lung cancer; but experiment verification should be performed in future." (PMID 32299382, 2020). "MiR‐646 is downregulated in non‐small cell lung cancer (NSCLC) and could suppress the proliferation and EMT‐induced metastasis of NSCLC by suppressing FGF2 and CCND2." (PMID 32347652, 2020). "Our group has published data on FGF2, which identify this marker as an independent negative prognostic factor in lung cancer cells." (PMID 24575749, 2014). "Squamous lung cancer cells NCI-H520 (FGFR1 positive) internalized about two times more FGF2 and FGF2 dual warhead conjugate than control, FGFR1 negative HCC-15 cells." (PMID 30029518, 2018). "Finally, the expression of TS was not affected by the transfection of si-FGF2 in either PC9-MTA or H1993-MTA cells, which indicated that the upregulation of TS might be induced by mechanisms other than those regulated by increased expression of FGF2 in these lung cancer cells." (PMID 30838090, 2019).
Stroke (63 papers, 2008 to 2025). Sudden impairment of blood flow to a part of the brain due to occlusion or rupture of an artery to the brain. "DA has been linked to molecules which show angiogenic effects following stroke, such as FGF-2 and CART." (PMID 30034335, 2018). "In this study we provide evidence to support FGF-2 as a mechanism underlying the neural plasticity and neurorestorative properties of amphetamine in stroke." (PMID 25229819, 2014). "The expression of FGF‐2 and its receptor significantly increases after a stroke, promoting NSPC proliferation." (PMID 41427019, 2025). "Key EMT-related genes that were downregulated upon MMP-3 KO in male stroke brains included Fbn1, Fbln1, Tgfb1, Tgfbr3, Snai2, and Fgf2." (PMID 39000490, 2024). "Since stroke-related increases in FGF2 expression are well known, downregulation at this time point is provocative and requires confirmation." (PMID 38548341, 2024). "It has also been shown that increased FGF-2 expression in a rat stroke model leads to increased neurogenesis and can lead to the recovery of brain function following a stroke." (PMID 36980690, 2023). "Since no attempt was made to re-engineer the neurotrophin for BBB delivery, the trials met with the expected failed results for either the intravenous fibroblast growth factor (FGF)-2 stroke trial or the intravenous erythropoietin (EPO) stroke trial." (PMID 35745855, 2022). "Overall, main FD features including hypertrophic cardiomyopathy, venous thrombosis, arterial thrombosis, and stroke, cornea verticilata, and renal (chronic kidney disease stage) events are partly explained by FGF2, IL-7, VEGFA, and VEGFC plasma levels." (PMID 32370284, 2020). "In our study, we found OPN increased the proliferation in monolayer cultures of primary NSC grown in the presence of FGF2, and additionally in the rat brain after stroke in vivo." (PMID 25998490, 2015). "Studies are currently underway to directly test the therapeutic potential of FGF-2 upregulation in motor rehabilitation following stroke." (PMID 25229819, 2014). "Compared with the stroke group, the mRNA expression levels of FGF-2 in the frontal cortex tissue of the PSD rats were significantly decreased (P<0.01; Student’s t-test)." (PMID 24944615, 2014). "Through western blotting, the protein expression levels of FGF-2 in the frontal lobe were found to be significantly lower than those in the stroke group (P<0.01; Student’s t-test)." (PMID 24944615, 2014). "We found that, following stroke in rats, short-term amphetamine paired with physical therapy induced an increase in the number of FGF-2 expressing pyramidal neurons in the unlesioned motor cortex as compared to physical therapy alone." (PMID 25229819, 2014). "In the frontal lobe tissue, the FGF-2 protein expression levels in the PSD group were significantly lower than those in the stroke group (P<0.01; Student’s t-test)." (PMID 24944615, 2014). "Given this information, it seems reasonable to suggest that FGF-2 plays a key role in the development of neural plasticity related to motor rehabilitation following brain damage, such as in stroke." (PMID 25229819, 2014). "Despite such intriguing results there has been little follow-up investigation on a “neurorestorative” role for FGF-2 in rehabilitative therapy following stroke." (PMID 25229819, 2014). "Central administration of FGF-2 within 24 hr of experimental stroke has been shown to improve motor recovery and upregulate growth-associated protein 43, a marker of axonal growth." (PMID 25229819, 2014). "Subsets of animals were sacrificed at 2 weeks post-stroke and 8 weeks post-stroke (end-point) for stereological assessment of FGF-2 expressing cells in the contralesional cortex, which represents the origin of new corticomotor pathways." (PMID 25229819, 2014). "Perhaps, food-deprivation-mediated FGF2 upregulation may reduce brain damage and improve functional outcome in stroke model, protecting neural cells and enhancing synaptic plasticity." (PMID 35334932, 2022).